PRL (prolactin)
Diseases named in the same sentence as PRL in open-access papers (continued):
Sharing a sentence is not in itself a finding about the gene and the disease.
hyperprolactinemia (continued). "Diagnosed with hyperprolactinemia secondary to a prolactinoma, IGM patients in two case reports improved after treatment with prolactin inhibitors." (PMID 38529282, 2024). "Although the evidence for whether or not hyperprolactinemia and its magnitude are per se associated with increased breast cancer risk is lacking, clinicians should proactively monitor for hyperprolactinemia and breast cancer risk when prescribing prolactin-raising antipsychotics." (PMID 38687213, 2024). "One of the most frequent side effects of atypical antipsychotics is hyperprolactinemia (HPRL), and metformin or aripiprazole co-prescription is regarded as an effective therapy option for reducing prolactin (PRL) levels." (PMID 36816406, 2023). "In fact, in men, an acute increase in PRL may have physiological inhibiting consequences for sexual function specifically in the post-orgasmic phase, acting through a feedback to dopaminergic neurons, while hyperprolactinemia is consistently correlated with low sexual desire." (PMID 37204690, 2023). "Prolactin axis dysfunction is frequent (22.8%) but may be underestimated as one study showed no prolactin dysfunction in 26 patients after a median follow-up of 2.7 years, and two studies reported hyperprolactinemia only in women for tumors both close and distant to the HP axis." (PMID 37568636, 2023). "Both groups were comparable with respect to age, reasons for hyperprolactinemia, smoking, BMI, blood pressure, HOMA1-IR, and plasma levels of glucose, total prolactin, monomeric prolactin, macroprolactin, FSH, SHBG, thyrotropin, ACTH and IGF-1." (PMID 37685540, 2023). "NLs block D2 receptors leading to hyperprolactinemia and a reduction in APO–PRL, GH and ACTH/cortisol responses." (PMID 37239772, 2023). "Because hyperprolactinemia is also present in patients with first-episode SCZ, some prolactin elevating antipsychotics have been shown to have a cancer-protective mechanism." (PMID 36138824, 2022). "According to our results, there is a positive correlation between PRL levels and DFI value, however, further studies are needed, especially in the hyperprolactinemia individuals after complete treatment." (PMID 36819202, 2022). "Additionally, the study determining hyperprolactinemia after 1 and 7 d of HS was conducted in younger growing pigs, while reduced PRL was identified due to HS in late gestation sows; thus, age and developmental status of the female could be another potential contributing factor." (PMID 35772766, 2022). "This process highlights the importance of inflammatory regulators in pathological alterations of the PRL system, by “highjacking” the TIDA circuit and ultimately promoting hyperprolactinemia." (PMID 35173591, 2022). "Even though normalization of PRL concentrations by DA therapy can improve BMD and can reduce the risk of fracture, it may be necessary to treat specifically osteoporosis with the same therapeutic options as in the general population in addition to the treatment for hyperprolactinemia." (PMID 35000899, 2022). "Hyperprolactinemia (HPRL) is characterized by dysfunction of the hypothalamic-pituitary-reproductive axis and mainly refers to serum levels of PRL that exceed normal values (PRL > 25 ng/ml)." (PMID 35465073, 2022). "Indeed, hyperprolactinemia could be determined not only by PRL-secreting pituitary adenomas, but also by numerous other conditions involving physiological status such as pregnancy and lactation, systemic disorders like chronic renal failure and cirrhosis or several pharmacological treatments." (PMID 36237192, 2022). "A positive correlation between PRL and anti-dsDNA antibody concentrations has been demonstrated in SLE patients, and women with hyperprolactinemia have a higher prevalence of autoantibodies." (PMID 36389691, 2022).
hyperprolactinemia (continued). "Moreover, as a suitable alternative for OLZ-induced hyperprolactinemia, aripiprazole may not only diminish PRL levels but may also clear PRL-related symptoms that may occur with borderline or normal standardized PRL values while maintaining clinical stabilization." (PMID 36313772, 2022). "Women with coincident PCOS and hyperprolactinemia appear more insulin resistant than women with PCOS and normal prolactin levels." (PMID 36457554, 2022). "Currently, dopamine agonists (DAs) are highly effective in normalizing prolactin (PRL) and ameliorating the symptoms of hyperprolactinemia." (PMID 35741585, 2022). "Histological analysis of this tissue revealed increased size of lipid droplets within brown adipocytes, in response to either hyperprolactinemia or HFD independently, and, importantly, prolactin further increased lipid droplet size after exposure to an HFD." (PMID 35757410, 2022). "Recently, it is reported that BSZY-D can reduce the prolactin (PRL) level in patients with luteal phase defect and hyperprolactinemia (HPRL) in clinic practice." (PMID 34424219, 2021). "Moreover, we have shown that hyperprolactinemia caused by absence of Prlr in the forebrain also induces beta-cell expansion and “pregnancy-like” changes in glucose homeostasis, further evidence for a direct action of elevated prolactin in the pancreas." (PMID 34867810, 2021). "Age, sex, body mass index, tumor size, invasiveness, prolactin staining, ki-67 index, and GH/IGF-1 levels were significantly correlated with preoperative hypopituitarism and hyperprolactinemia." (PMID 35154007, 2021). "The knowledge about prolactin levels in PWS is sparse, and the aim of this study was to characterize adults with PWS and hyperprolactinemia." (PMID 34441908, 2021). "Although hyperprolactinaemia of extracranial origin is exceptionally rare, it should be suspected in patients found to have very high (> 10× ULN) serum prolactin concentrations and normal findings on cranial imaging." (PMID 32857272, 2020). "Among antipsychotics, prolactin-raising (PR) antipsychotics, are more likely to influence BMD of patients, due to antipsychotic-induced hyperprolactinemia and/or secondary hypogonadism." (PMID 30846868, 2019). "False or pseudohyperprolactinaemia is defined with post-PEG PRL within post-PEG reference intervals and true hyperprolactinaemia above the upper limit of the post-PEG reference interval." (PMID 31223260, 2019). "Significant higher level of prolactin was found in FEP group than in CHR group (mean = 28.93 ± 27.16 vs 14.29 ± 7.86, P = 0.009), suggesting a condition of hyperprolactinemia (HPRL)." (PMID 30068291, 2018). "Transient hyperprolactinemia has been proven to adversely affect the outcome of IVF, and studies have concluded that patients with normal serum prolactin levels had higher fertilization and cleavage rates." (PMID 29739353, 2018). "While other researchers found the effect of increased serum prolactin during IVF to be insignificant, subsequent studies found a positive effect of transient hyperprolactinemia on the outcome of ovarian simulation in IVF." (PMID 29739353, 2018). "Investigators reported hyperprolactinemia in two patients in the OLA group and three patients in the prior Pali ER group and an increase in blood prolactin in two patients in the prior ARI group." (PMID 27815602, 2017). "On the other hand, suckling, which induces hyperprolactinemia, can stimulate the activation of hypothalamic NPY neurons, suggesting that NPY is modulated by prolactin (PRL) during lactation." (PMID 29383163, 2017). "Consistent with the fast-dissociation hypothesis of APD atypicality, we found that hyperprolactinemia was correlated with the dissociation rate (koff), with ligands that were the slowest to dissociate from the D2R displaying the greatest liability for prolactin elevation in patients." (PMID 28970469, 2017).
hyperprolactinemia (continued). "Therefore, in this study, we aimed to observe the clinical effect of PGD on Amisulpride-induced hyperprolactinemia in female schizophrenia patient, then detect the changes of levels of PRL and other related hormones, and assess whether it is safe and reliable or not." (PMID 29317896, 2017). "Having recognized the significant prevalence of hyperprolactinemia in the CKD stage 5-D population, bromocriptine has been investigated in the past as a treatment option in view of its ability to suppress prolactin levels." (PMID 28382300, 2017). "Patient number 25 was initially very sensitive to BRC treatment, and the PRL level decreased to the normal range; after BRC withdrawal, the patient experienced hyperprolactinemia and tumor recurrence, and BRC therapy was readministered." (PMID 27999593, 2016). "Consequently, the metabolic effects of timed daily bromocriptine treatment observed in this study may in part derive from a reduction of plasma hyperprolactinemia and normalization of the daily rhythm of plasma prolactin level towards that of lean, insulin sensitive rats." (PMID 25937836, 2014). "While one of the patients in the present study exhibited a markedly elevated PRL level of 163.5 ng/ml, her PEG-precipitated PRL (44.15%) was the highest of all of the patients with hyperprolactinemia." (PMID 24312671, 2013). "Hyperprolactinemia has been confirmed in SLE patients (20%–30%), and those with active SLE display higher serum PRL levels." (PMID 21799742, 2011). "Although the basal secretion level of PRL was within the normal range, an over-response in PRL secretion was noted in the TRH provocation test, suggesting latent hyperprolactinemia." (PMID 22152284, 2011). "Other studies have shown hyperprolactinemia at PND30 in males treated prenatally with BPA, whereas others reported an increase in serum PRL in adult females ovariectomized and treated with BPA." (PMID 19479018, 2009). "Repeated cannulated prolactin sampling may rule out some of these causes of hyperprolactinemia at initial diagnosis, but also during evaluation of treatment success—particularly in cases with recovery of the gonadal axis in the absence of complete normalization of prolactin levels." (PMID 41017446, 2026). "In contrast, prolactin normalization rates in men suffering from symptomatic hyperprolactinemia without a visible pituitary adenoma on imaging have been reported to be 100.0%." (PMID 40199840, 2025). "Given that hyperprolactinemia is observed in some PCOS phenotypes, future studies should explore whether prolactin directly influences vasorin expression, potentially providing insights into PCOS heterogeneity." (PMID 40137147, 2025). "Hyperprolactinemia in patients with PCOS may additionally aggravate the decline in insulin sensitivity, attributable to prolactin lipogenic effects and influence on metabolic profile." (PMID 40362476, 2025). "Hyperprolactinaemia is frequently found in FEP patients and could be an epiphenomenon of an acute stress response, stress triggering prolactin release." (PMID 40896214, 2025). "The study included men with only mild or moderate prolactin excess but not individuals with severe hyperprolactinemia, which is often complicated by gonadal failure." (PMID 39204081, 2024). "Age does not appear to influence prevalence rates of hyperprolactinemia in men, but a decline of prolactin level with age was observed in women, suggesting a postmenopausal effect." (PMID 38221595, 2024). "Although we cannot completely rule out a PRL-increasing effect of testosterone, we chose not to use the term “drug-induced hyperprolactinemia”." (PMID 39857650, 2024). "In a more recent study, involving 214 patients with nonfunctioning pituitary adenomas, preoperative hyperprolactinemia was found in 93 cases (43.5%), and median serum prolactin concentration was 34.68 ng/mL (range, 0.23-213.90 ng/mL)." (PMID 39420933, 2024).
hyperprolactinemia (continued). "After the last pregnancy, in 21/43 women (48.8%), remission of hyperprolactinemia, defined as normalization of PRL levels, was documented in the absence of therapy, while disease persistence was found in 22/43 (51.2%)." (PMID 38499816, 2024). "HP: hyperprolactinemia, mPRL: macroprolactinemia, F: female, M: male, BMI: body mass index, Cr: creatinine, TSH: thyroid stimulating hormone, ALT: alanin aminotransferase, AST: aspartate aminotransferase, PRL: prolactin, IQR: interquartile range." (PMID 39552974, 2024). "The main aim of this study was to assess the usefulness and accuracy of the magnitude of prolactin level in predicting the etiology of nonphysiological hyperprolactinemia." (PMID 39420933, 2024). "The finding of hyperprolactinaemia in pemphigus vulgaris has been replicated in several studies in up to 22% of patients, although a correlation between serum PRL and desmoglein 3 and 1 antibodies was not identified." (PMID 39000207, 2024). "Given the negative consequences of hyperprolactinemia, and the possibility for reasonable modifications to antipsychotic regimens, we suggest routine monitoring of prolactin in patients who are prescribed antipsychotics." (PMID 38352655, 2024). "It is important to note that none of these patients had a PRL > 47 ng/mL and can thus all be classified as mild-to-moderate hyperprolactinemia." (PMID 39857650, 2024). "Furthermore, elevated prolactin levels, common in CKD, exacerbate this issue, as hyperprolactinemia reduces gonadotropin secretion leading to ED and hypogonadism." (PMID 38649741, 2024). "Recently, a randomized controlled trial assessed the efficacy of metformin in treating hyperprolactinemia induced by amisulpride, yielding positive conclusions that metformin can effectively reduce serum prolactin levels without significant adverse effects." (PMID 38505795, 2024). "In these cases, the prolactin level is the marker distinguishing macroprolactinomas from nonfunctioning pituitary macroadenomas (in which hyperprolactinemia occurs due to pituitary stalk disconnection)." (PMID 38578472, 2024). "The prolactin levels in patients with hyperprolactinemia and nonfunctioning pituitary adenomas (n = 70) ranged from 39 to 250 ng/mL (mean, 86.97 ± 45.14 ng/mL; median, 77 ng/mL)." (PMID 39420933, 2024). "The aim of this study was to evaluate the usefulness and accuracy of prolactin levels in predicting the etiology of nonphysiological hyperprolactinemia." (PMID 39420933, 2024). "In contrast, the non-PCOS group with hyperprolactinemia revealed both a decrease in the homeostatic model assessment of insulin resistance and PRL, suggesting that testosterone impaired the PRL decrease." (PMID 39857650, 2024). "Hyperprolactinemia in FGA could be due to the stalk effect, prolactin cosecretion, or hyperestrogenemia." (PMID 37988667, 2023). "Similar to hyperprolactinemia in humans, which can be reversed with BCR therapy, the highest secretion of PRL in rams during the summer solstice may have detrimental effects on sperm." (PMID 37954671, 2023). "However, the prevalence of hyperprolactinemia would have remained almost the same even if we had adjusted for this, as OCP only minimally increase prolactin levels." (PMID 37854182, 2023). "Lastly, a significant negative correlation between serum PRL levels and executive functions was found in prolactinoma patients, suggesting the toxic effect of hyperprolactinemia on cognitive functions." (PMID 37250398, 2023). "The proportion of patients with hyperprolactinaemia and mean serum PRL levels were not significantly different between the different BMI subgroups." (PMID 36845388, 2023). "In the present study, there was no significant variance between SLE patients with normal prolactin levels and those with hyperprolactinemia regarding age or any laboratory findings." (PMID 37864188, 2023).
hyperprolactinemia (continued). "Hyperprolactinemia was found in 8 patients (20%) but not in controls; 4 out of 8 patients with hyperprolactinemia (50%) showed neurological manifestations compared to only 3 out of 32 patients with a normal prolactin level (9.4%) (P value = 0.007)." (PMID 37864188, 2023). "Future studies are necessary to clarify apparently divergent laboratory and clinical data and to establish the optimal serum prolactin level for the best IVF outcome in patients with hyperprolactinemia preceding the IVF treatment and those with transient hyperprolactinemia during IVF." (PMID 36678618, 2023). "Along this same line, studies comparing acromegaly patients with and without hyperprolactinemia described an age 3 to 5 years younger in the group of GH–PRL PitNETs compared with GH PitNETs." (PMID 37762304, 2023). "Since 72.3% of patients with hyperprolactinemia had TSH levels in the upper range (>4.2 mIU/L), it may be hypothesized that macro-TSH was present in the samples due to the cross-reactivity of anti-PRL antibodies." (PMID 37511458, 2023). "Although PRL could induce estrogen receptor-positive breast cancer (BC) in a murine model, and initiate the transformation of normal ductal epithelial cells, many epidemiological studies have not shown an increased risk of BC in the population with hyperprolactinaemia." (PMID 36845388, 2023). "Since a symptom of hyperprolactinemia is depression, there have been suggestions that depression in patients with HIV could be correlated with high PRL levels, but a recent meta-analysis disproved this." (PMID 36833950, 2023). "Our data showed that the proportion of patients with hyperprolactinaemia and mean serum PRL levels were not significantly different between malignant and benign lesions in premenopausal patients." (PMID 36845388, 2023). "One tumour co-expressed TSH, GH and PRL without evidence of hyperthyroidism or hyperprolactinaemia clinically or biochemically." (PMID 37851558, 2023). "Because the study population included a heterogenous group of women with prolactin excess, it cannot be completely ruled out that the impact on prolactin levels partially depends on the reason for hyperprolactinemia." (PMID 37297964, 2023). "In this respect, normal baseline PRL level is a good index of the lack of residual impregnation of antipsychotics, given these drugs block D2 receptors and induce hyperprolactinemia." (PMID 37239772, 2023). "Taking into account the negative impact of high prolactin levels on fertility and the complex involvement of prolactin in reproduction, several studies evaluated the relationship between transient hyperprolactinemia during COS and IVF outcomes." (PMID 36678618, 2023). "Prolactin cosecretion in FGAs is very rare, and the negative immunostaining for prolactin in our patient refuted this possibility, whereas hyperprolactinemia > 200 ng/mL is unusual due to stalk compression alone." (PMID 37988667, 2023). "Various strategies for lowering prolactin levels diminish the negative long-term effects of hyperprolactinemia." (PMID 37759839, 2023). "It seems that treatment of hyperprolactinemia does not negatively impact the pregnancy rate, although the effect of persistently high prolactin levels on oocyte quality is controversial." (PMID 36678618, 2023). "Domperidone stimulates prolactin secretion potentially via dopaminergic mechanism by inhibiting the prolactin inhibiting factor (PIF) at the level of hypothalamus, consequently fostering uninhibited prolactin release i.e., hyperprolactinemia." (PMID 38249246, 2023). "There were no between-group differences in age, smoking habits, reasons for hyperprolactinemia, the body mass index, blood pressure, glucose, HOMA1-IR, thyrotropin, free thyroid hormones, total prolactin, monomeric prolactin, macroprolactin, FSH, LH, ACTH and IGF-1." (PMID 37297964, 2023).